AKAP4 (A-kinase anchoring protein 4)
Description:
Major structural component of sperm fibrous sheath. Plays a role in sperm motility.
Synonyms: AKAP-4; AKAP 82; hAKAP82; HI; PRKA4; AKAP82; p82; Fsc1; CT99
Tractability: No criterion of Open Targets' tractability assessment is met for any kind of drug.
Gene: Protein-coding gene on chromosome X (50,190,777 to 50,201,007, reverse strand). Ensembl gene ENSG00000147081.
Subcellular location: Cell projection, cilium, flagellum
Subcellular location (Human Protein Atlas): Principal piece
Gene Ontology:
Molecular function: protein binding; protein kinase A binding
Biological process: flagellated sperm motility; cell surface receptor protein serine/threonine kinase signaling pathway; intracellular protein localization; signal transduction; single fertilization; spermatogenesis
Cellular component: motile cilium; nucleus; sperm end piece; sperm fibrous sheath; sperm flagellum; sperm head-tail coupling apparatus; sperm midpiece; sperm principal piece; cAMP-dependent protein kinase complex; cytoplasm; cytoskeleton; cilium; perinuclear region of cytoplasm; Z disc
Homologues: Orthologues: chimpanzee AKAP4 (98% identical), macaque AKAP4 (95% identical), pig AKAP4 (82% identical), mouse Akap4 (78% identical), rat Akap4 (78% identical), guinea pig AKAP4 (74% identical). Paralogues in human: AKAP3 (35% identical), SPHKAP (20% identical), AKAP11 (16% identical).
Diseases named in the same sentence as AKAP4 in open-access papers:
AKAP4 is named in the same sentence as 34 diseases in open-access papers, as found by Europe PMC text mining. Sharing a sentence is not in itself a finding about the gene and the disease. The quoted sentences say what the papers report.
male infertility (9 papers, 2020 to 2025). The inability of the male to effect fertilization of an ovum after a specified period of unprotected intercourse. "Oxidative stress will destroy the AKAP4 which results in the defective sperm function associated with male infertility." (PMID 38027210, 2023). "Reduced AKAP4 and QRICH2 protein levels cause dysplasia of the fibrous sheath, which ultimately leads to decreased sperm motility and male infertility." (PMID 37174638, 2023). "Intersection of genes from transcriptomic studies with genes with identified rare variants revealed a total of 7 genes linked with male infertility phenotype (CYP11A1, CYP17A1, RSPH3, TSGA10, AKAP4, CCIN, NDNF)." (PMID 37670815, 2023). "According to the literature, there has been limited evidence for the association of AKAP4, CCIN and NDNF genes with male infertility." (PMID 37670815, 2023). "In the AKAP family, AKAP3 and AKAP4 mutations were identified causing dysplasia of the fibrous sheath, presenting MMAF phenotypes and male infertility." (PMID 35955660, 2022). "We further analyzed the relationship between downregulated proteins and human reproductive diseases by DisGeNET and Cytoscape and found that proteins such as Odf1, Odf1, and Akap4 were involved in asthenozoospermia, teratozoospermia, and male infertility." (PMID 34268309, 2021). "Knockouts of EL52, AKAP4, ODF2 and HSPA2 showed phenotypic alterations in sperm physiology and morphology, which resulted in male infertility." (PMID 34697378, 2021). "A recent systematic review demonstrated that many sperm proteins associated with male infertility—particularly those involved in oxidative stress regulation and mitochondrial function (e.g., PRDX6, SOD1, AKAP4)—are not detected by routine semen analysis." (PMID 41011106, 2025). "Collectively, these results indicated that these proteins AKAP4, ODF1, ODF2, GAPDHS, SPESP1, and ACTRT2 were significantly down-regulated after heat treatment of scrotum, suggesting that these proteins may serve as the biomarkers for scrotal heat treatment-induced male infertility." (PMID 32787870, 2020).
infertile (8 papers, 2018 to 2025). "This scaffold protein is instrumental in regulating sperm flagellum motion and an AKAP4 deletion results in a defective fibrous sheath formation and flagellar dysplasia, resulting in infertility due to the loss of motility and sperm abnormalities." (PMID 35622752, 2022). "A kinase anchor protein 4 (Akap4)-deficient mice are infertile due to a poorly developed fibrous sheath and a short flagellum in the spermatozoa." (PMID 29661171, 2018). "AKAP4 knocked-out animals are reported to show sperm tail alterations and modified tail thickness, resulting in immotile spermatozoa and then in infertile animals." (PMID 40281994, 2025). "Furthermore, studies on mice models reported a relationship between induced defects in the AKAP4 gene and sperm flagellum alterations, resulting in immotile spermatozoa and mice infertility." (PMID 40281994, 2025). "Among them, proAKAP4, which is the precursor of AKAP4, the main structural protein in the fibrous sheath of spermatozoa; appears to be promising, especially since spermatozoa lacking AKAP4 expression were shown to be immotile, abnormal, and infertile." (PMID 35622752, 2022). "In humans, AKAP4 is clearly downregulated in infertile patients with asthenozoospermia." (PMID 35622752, 2022). "Interestingly, AKAP4 was highly represented in the spermatozoa of fertile compared with infertile men that had lost the capacity to bind in vitro to the zona pellucida." (PMID 35622752, 2022). "Moreover, mutations or partial deletions of some X-linked genes such as AKAP3, AKAP4, NXF2, TAF7L, USP26, and TEX11 are linked to male subfertility or infertility." (PMID 29661171, 2018). "However, some researchers believe that men lacking the Akap4 gene are usually infertile, and their sperm count and sperm survival are greatly reduced." (PMID 40567906, 2025). "Moreover, the subcellular distributions of PKA catalytic subunits and regulatory subunits, such as PI3K, were disrupted and there were significant changes in PP1gamma2 activity and phosphorylation in immotile sperm from infertile mice lacking AKAP4." (PMID 33023073, 2020). "The importance of AKAP4 in the organization and integrity of the fibrous sheath has been elegantly highlighted by gene ablation studies in which male mice lacking AKAP4 are rendered infertile due to lesions in the progressive motility profiles of their spermatozoa." (PMID 31921838, 2019).
breast carcinoma (7 papers, 2013 to 2022). "FSIP1 is a component of fibrous sheath in sperm flagellum that assembles AKAP4, which was the original X-linked CT antigen detected in breast cancer." (PMID 25826084, 2015). "We further investigated humoral response in breast cancer patients by Enzyme Linked Immuno-Sorbent Assay (ELISA) after validating AKAP4 protein expression in tissue specimens." (PMID 23451156, 2013). "Moreover our recent studies on well characterized CT antigens, SPAG9 and AKAP4 have shown their association with breast cancer cases." (PMID 27658496, 2016). "Therefore, this investigation was undertaken to assess the association of AKAP4 with various clinical parameters in order to develop tissue or serum based early detection biomarker for better cancer treatment modalities in breast cancer patients." (PMID 23451156, 2013). "Collectively, our data suggests that AKAP4 may be used as serum based diagnostic test for an early detection and diagnosis of breast cancer and may be a potential target for immunotherapeutic use." (PMID 23451156, 2013). "Recently, AKAP4 has been proven to be a promising diagnostic and prognostic biomarker for colorectal cancer, NSCLC, breast cancer, and ovarian serous carcinoma." (PMID 35253625, 2022). "AKAP4 expression is detected at high rate in various breast cancer tumors and has been suggested as a biomarker for breast and prostate cancer." (PMID 29433456, 2018). "Anti-AKAP4 antibodies were found in majority of patients with early stage (81%) as well as late stage breast cancer (77%)." (PMID 23451156, 2013). "We further examined the localization of AKAP4 protein in breast cancer cells by indirect immunofluorescence assay and flow cytometric analysis." (PMID 23451156, 2013). "Sera from 91 breast cancer patients and from 45 healthy normal donors were subjected to ELISA for detecting anti-AKAP4 antibodies." (PMID 23451156, 2013). "AKAP4 gene expression was investigated in human normal mammary epithelial cells and breast cancer cells of two different origins namely adenocarcinoma (MCF7, MDA-MB-231 and SK-BR3), and ductal carcinoma (BT474)." (PMID 23451156, 2013). "In contrast, AKAP4 expression was observed in majority of breast cancer patients (85%) indicating its potential role in tumorigenesis." (PMID 23451156, 2013). "In this regard, our investigation on CT-X antigen AKAP4 revealed that AKAP4 was immunogenic and generated humoral response in majority of breast cancer patients, as compared to healthy donors (P<0.001, Pearson’s Chi-square test)." (PMID 23451156, 2013). "In this context, we investigated an association of cancer testis antigen, A-Kinase anchor protein 4 (AKAP4) with breast carcinoma." (PMID 23451156, 2013). "Statistical analysis of AKAP4 expression and humoral response with different clinical characteristics of breast cancer." (PMID 23451156, 2013). "Polyclonal anti-AKAP4 antibody raised in rats was used to probe the AKAP4 protein in breast cancer cell lysates." (PMID 23451156, 2013). "AKAP4 expression in breast cancer in all clinicopathological stages and grades indicates its possible role in tumorigenesis and disease progression." (PMID 23451156, 2013). "Our results distinctly revealed cytoplasmic localization of AKAP4 in 85% (77/91) of breast cancer patients." (PMID 23451156, 2013). "AKAP4 gene expression was investigated in breast cancer patient’s tissue specimens by employing in situ RNA hybridization." (PMID 23451156, 2013). "Our data indicated the presence of circulating anti-AKAP4 antibodies in 79% (79/91) of the breast cancer patients." (PMID 23451156, 2013). "For indirect immunofluorescence, breast cancer cells were fixed, permeabilized and probed with anti-AKAP4 antibodies." (PMID 23451156, 2013). "In the present study, we investigated the AKAP4 expression in various histotypes of breast carcinoma." (PMID 23451156, 2013).
breast carcinoma (continued). "AKAP4 gene expression was validated for endogenous AKAP4 protein expression in all breast cancer cells by using Western blotting." (PMID 23451156, 2013). "We first compared the AKAP4 gene and protein expression in four breast cancer cells (MCF7, MDA-MB-231, SK-BR3 and BT474) and normal human mammary epithelial cells." (PMID 23451156, 2013). "In our study, in situ RNA hybridization results revealed AKAP4 gene expression in 85% of total breast cancer patients." (PMID 23451156, 2013). "A-Kinase Anchor Protein 4 (AKAP4) was also determined as overexpressed in breast cancer tissues using immunohistochemistry and ELISA assay showed that anti-AKAP4 autoantibodies were elevated in sera of patients, making them a potential biomarker for early detection and diagnosis." (PMID 24550697, 2014). "Humoral response against AKAP4 was also investigated in breast cancer patients employing ELISA." (PMID 23451156, 2013). "AKAP4 gene expression was detected in 85% (77/91) of breast cancer patients." (PMID 23451156, 2013). "Clinopathologic features, AKAP4 expression and humoral response in breast cancer." (PMID 23451156, 2013). "We further extended our analysis of AKAP4 expression in different grades of breast cancer samples." (PMID 23451156, 2013). "All breast cancer cell lines revealed cytoplasmic localization of AKAP4 protein." (PMID 23451156, 2013). "Therefore, our findings of anti-AKAP4 antibodies in 79% of breast cancer patients are important from a clinical standpoint to develop novel assays for early diagnosis, and effective disease management." (PMID 23451156, 2013). "Interestingly, we observed that 94% (72/77) of breast cancer patients found positive for AKAP4 protein expression generated humoral response against AKAP4 protein." (PMID 23451156, 2013). "The surface localization of AKAP4 protein suggests that it may be a potential target candidate for therapeutic use in breast cancer patients." (PMID 23451156, 2013). "Given consistencies in AKAP4 gene and protein expression, expression in various histotypes, different stages and grades of breast cancer, and humoral response against AKAP4 in breast cancer patients illustrates its potential diagnostic role as a biomarker in clinical settings." (PMID 23451156, 2013). "The immune-privileged characteristic of testis and abundant expression of AKAP4 in breast cancer may provide the lead for further development of novel serum based tumor biomarker and might be a potential immunotherapeutic target." (PMID 23451156, 2013). "AKAP4 protein expression was found in 87% early stages (stage I+II) and 82% late stages (stage III+IV) breast cancer patients." (PMID 23451156, 2013). "A number of these AKAPs have been reported to correlate with the occurrence of different cancer subtypes, including AKAP3 (ovarian cancer), AKAP4 (multiple myeloma), AKAP9 (breast cancer), AKAP10 (breast cancer) and AKAP13 (colorectal cancer and breast cancer)." (PMID 26272591, 2015). "Our results revealed AKAP4 gene expression in all four breast cancer cell lines (MCF7, MDA-MB-231, SK-BR3 and BT474), but not in normal mammary epithelial cells." (PMID 23451156, 2013). "AKAP4 protein expression was detected in all the breast cancer cell lines but not in normal breast epithelial cells." (PMID 23451156, 2013). "Using in situ RNA hybridization and immunohistochemistry, 85% (77/91) tissue specimens irrespective of histotypes, stages and grades of breast cancer clinical specimens revealed AKAP4 gene and protein expression." (PMID 23451156, 2013). "It is noteworthy that we did not observe discrepancy between AKAP4 gene and protein expression in breast cancer specimens under investigation." (PMID 23451156, 2013). "We demonstrated AKAP4 expression (85%) and humoral response (79%) in breast cancer patients irrespective of their histotypes, grades and stages." (PMID 23451156, 2013).
breast carcinoma (continued). "Interestingly, the more prevalent breast cancer, IDC also revealed AKAP4 gene expression in majority of IDC cancer patient’s specimens under investigation." (PMID 23451156, 2013). "In addition, AKAP4 is a novel CTA that is abnormally expressed in multiple types of malignant tumors, including ovarian cancer, cervical cancer, multiple myeloma, breast cancer, and prostate cancer." (PMID 35253625, 2022). "In contrast, AKAP4 showed expression at the gene and protein level in majority of breast cancer patients (85%) irrespective of histotypes, stages and clinical grades of breast cancer, suggestive of its potential as a biomarker and therapeutic candidate." (PMID 23451156, 2013). "Moreover, due to the heterogeneity observed in breast cancer tissues, some of the patients did not generate humoral response against AKAP4." (PMID 23451156, 2013). "We demonstrated that majority of breast cancer patients showed AKAP4 expression irrespective of clinical stages and histological grades of tumor suggesting that AKAP4 may have a potential role in disease progression." (PMID 23451156, 2013).
prostate carcinoma (7 papers, 2013 to 2025). A carcinoma that arises from epithelial cells of the prostate gland. "In this regard, AKAP4 was recently shown to be associated with multiple myeloma, prostate cancer and lung cancer." (PMID 23451156, 2013). "Beyond androgen receptor–targeting peptides, MSS1—an optimized AKAP4-mimetic peptide developed to modulate sperm motility—also decreased prostate cancer cell viability." (PMID 41092058, 2025). "AKAP4 is a cancer testes antigen that can be detected in cervical, ovarian, breast and prostate cancers." (PMID 31384238, 2019). "For example, AKAP-4 was also highly expressed in prostate cancer cells and served as a potential target for prostate cancer adoptive immunotherapy or anti-tumor vaccination." (PMID 25900241, 2015). "Further, recently in agreement with our observations, it was reported that AKAP4 was immunogenic in multiple myeloma (36%) and prostate cancer patients (67%)." (PMID 23451156, 2013). "Similarly to our previous study of SP17 in non-small cell lung cancer and AKAP-4 in prostate cancer, we at first evaluated SP17 immunogenicity by detecting serum anti-SP17 autoantibodies in HNSCC patients." (PMID 29245977, 2017).
non-small cell lung carcinoma (6 papers, 2015 to 2023). A group of at least three distinct histological types of lung cancer, including non-small cell squamous cell carcinoma, adenocarcinoma, and large cell carcinoma. "Intriguingly, it has been shown that SP17/AKAP4/PTTG1 could induce an immunogenic response in non-small cell lung cancer patients." (PMID 35768832, 2022). "In this study we investigated the expression and immunogenicity of the CTAs, Sperm Protein 17 (SP17), A-kinase anchor protein 4 (AKAP4) and Pituitary Tumor Transforming Gene 1 (PTTG1) in human non-small cell lung cancer (NSCLC) cell lines and primary tumors." (PMID 25739119, 2015). "To determine whether tumor derived CTA mRNAs could be detected in RNA from purified peripheral blood mononuclear cells (PBMC) of non-small cell lung cancer (NSCLC) patients, we assayed for the expression of 116 CTAs in PBMC RNA in a discovery set and identified AKAP4 as a potential NSCLC biomarker." (PMID 26160834, 2015).